IFNG (interferon gamma)
Diseases named in the same sentence as IFNG in open-access papers (continued):
Sharing a sentence is not in itself a finding about the gene and the disease.
tumor (continued). "Additionally, there was no longer a significant difference in IFNγ expression between PVR− or PVR+-K562 cell restimulation when anti-TIGIT antibodies were present in the initial tumor co-culture, indicating that the initial difference was TIGIT-dependent." (PMID 37345049, 2023). "We analysed sensitivity to IFNγ and AC484 in each represented tissue type and found that cancers of the urinary tract, breast, skin, and head and neck were among the most sensitive, whereas tumours of the autonomic ganglia and the endometrium were the most resistant in vitro." (PMID 37794185, 2023). "In mice xenografted with cervical tumors and treated with ATRA and PDL1 Ab, MDSCs were diminished and tumor growth decreased, presumably mediated by high intra-tumoral infiltration of CD4+ and CD107a+CD8+ cytotoxic T-cells and the production of pro-inflammatory cytokines (IFNγ, TNFα)." (PMID 37686465, 2023). "However, pretreatment of the tumor cells with IFNγ did not lead to increased responsiveness to checkpoint treatment; thus, the effect was not fully explained by increased MHC class I on the tumor cells, but rather activation of a broad range of immune cells." (PMID 36546872, 2023). "We believe that the ECM-bound IFNγ could not be extracted from the tumor tissue as efficiently as free IFNγ." (PMID 36732425, 2023). "Consistent with the previous results, IRU CAR-T (+CsA) group showed a significantly higher frequency of IFNγ+TNFα+-secreting CAR-T cells than that in WT CAR-T (+CsA) group, supporting that IRU CAR-T could better control tumour progression with CsA." (PMID 38123592, 2023). "However, T cells isolated from Raji-experienced mice that exhibited Ramos regression did not respond via IFNγ ELISpot to K562 cells expressing HLA-A3, even though IFNγ responses were generated to Raji and Ramos tumor cells." (PMID 37087494, 2023). "CD8+ T lymphocytes can induce the death of tumor cells or cells infected by viral pathogens via class I major histocompatibility complex (MHC) recognition and produce inflammatory mediators (interleukin (IL)-2, interferon gamma (IFN-γ) and tumor necrosis factor alpha -TNF-α)." (PMID 37624201, 2023). "Importantly, however, the choice of immune checkpoint molecules and the resultant values of ke did not impact our conclusion that IFNG-mediated cell-cycle arrest was the main determinant of tumor control." (PMID 37182110, 2023). "Accordingly, in the absence of cDC1 or IFNγ signaling, Pant enhanced tumor growth." (PMID 37833072, 2023). "Anti‐tumour effects were assessed by measuring pathologic complete response (pCR), survival analysis, immunohistochemistry for E‐cadherin, VEGF, MMP9, MMP2 and Ki‐67, serum measurement of IFNγ and IL‐4, and gene expression analysis of CD105, VEGFa, VEGFR2 and COX2." (PMID 37581480, 2023). "Alternatively, IFNγ, and potentially other soluble factors, produced by vaccine-induced CD4 T cells may impact additional signaling pathways within tumors or other immune cell types to augment tumor killing." (PMID 37711623, 2023). "Also, TNBC patients had a significant negative correlation between miR-181a levels and IFNG mRNA levels, as well as the IFNG response scores in tumor tissues from TNBC patients." (PMID 37932806, 2023). "Yet, IFNγ further amplified the GD1a effects and augmented both IDO1 and PD-L1 expression on the DCs, indicating that IFNγ and GD1a may act in concert to further amplify the tumor immunosuppressive loop." (PMID 37266839, 2023). "Interferon gamma (IFNγ) released from CD8+ T cells downregulates the expression of SLC3A2 and SLC7A11, two subunits of the glutamate-cystine antiporter system xc-, impairs the uptake of cystine by tumour cells and, as a consequence, promotes tumor cell lipid peroxidation and ferroptosis." (PMID 38201582, 2023). "Therefore, we stained tumor sections for Cxcl9 and Cxcl10 from untreated KPC2a-bearing mice and mice treated with αPD-L1 or CD40 agonist as such therapies may enhance IFNγ, which induces Cxcl9/Cxcl10." (PMID 36472588, 2023).
tumor (continued). "To quantify the number of surviving or dead tumor cells in a tumor cell killing assay, we established K9TCCnRFP cells expressing nuclear-restricted RFP (nRFP) and confirmed the expression of endogenous cPD-L1 protein and mRNA in both K9TCC parental and K9TCCnRFP cells upon IFNγ treatment." (PMID 37377896, 2023). "Therefore, high IFNG can promote GBM progression and weaken tumor response to immunotherapy." (PMID 37122693, 2023). "For example, Kudo (2019b) found that activated CD8+ T cells released interferon gamma (IFN-γ) during the process of initial cellular immunity, which not only attacked tumor cells but also engaged with receptors on the surface of cancer cells to upregulate PD-L1 and inhibit antitumor effects." (PMID 37745297, 2023). "Given that IFNγ can exert a strong bystander effect, influencing not just antigen-positive cells, the protection by epacadostat may extend to remote tumor cells." (PMID 36812891, 2023). "The absence of an IFNγ signal protects tumor cells from recognition and attack by immune cells." (PMID 36875059, 2023). "At this point, the tumour tissue was still small and at a relatively early stage, and at this stage, it is plausible that IFNγ may be mainly effective in killing tumour cells rather than regulating blood vessels." (PMID 37056922, 2023). "Interestingly, while T-cells were a source of IFNγ, they did not appear to be the major source in these tumours." (PMID 36977556, 2023). "Consequently, immune exclusion occurs, and IFNγ is not released because CD8-positive cells do not target the tumor without detecting antigen presentation by the dendritic cells." (PMID 37190239, 2023). "In addition, the absence of BAFF will lead to the weakening of the immunosuppressive function of MDSCs in tumor bearing mice, which is manifested in the weakening of the ability to secrete immunosuppressive factor INOS, accompanied by the increase of CD8+ IFNγ+ T cells." (PMID 35725835, 2023). "While in vitro the Rac1-specific 5934 TCR-transduced T cells performed slightly better in cytotoxicity and IFNγ release, the Rac2-specific 22894 TCR-transduced T cells expanded significantly better in vivo and induced more potent regression of the Rac1P29S expressing tumor cells." (PMID 36875127, 2023). "Cytotoxic T cells upregulated expression of the receptor for programmed cell death ligand (PD-L1), programmed cell death protein 1, as well as Interferon gamma (IFN-γ) and IL-2 when co-cultured with dendritic cells cultured in conditioned media from tumor organoids, but not their normal counterpart." (PMID 37091337, 2023). "PARP14 inhibitor treatment would not be efficacious as a monotherapy, as PARP14 antagonism or knockdown did not affect the ex vivo growth of the tumour cell lines we evaluated, nor did monotherapy significantly alter their tumour growth potential, even following chronic IFNγ stimulation." (PMID 37752135, 2023). "To investigate whether the tracer dose impacts ICI outcomes, we followed CT26 tumor growth in ICI-treated BALB/c mice receiving 0 μg, 50 μg (the imaging dose), or 250 μg (a neutralizing dose) of cold anti-IFNγ antibody with a treatment scheme matching our imaging experiments." (PMID 38130991, 2023). "The interaction between PD-L1 expressed in tumor cells and PD-1 expressed in T cells inhibits the activity of effector T cells and increases the secretion of proinflammatory cytokines, such as tumor necrosis factor (TNF)-alpha, interleukin (IL)-2, and interferon-gamma (IFN-γ)." (PMID 36674491, 2023). "Due to the sustained increases of IFNγ noted with the combination of entinostat and NHS-IL12, a follow-up study investigated this combination therapy in TC-1/a9 (HPV E6/E7+), CMT.64 and RVP3 tumor models resistant to PD-1/PD-L1 blockade due to varying MHC-I and APM deficiencies." (PMID 38260854, 2023).
tumor (continued). "It has been shown that IFNγ released from CD8+ T cells downregulates the expression of two subunits (SLC3A2 and SLC7A11) of the glutamate-cystine reverse transporter system xc, which inhibits tumor cell cystine uptake and thus promotes lipid peroxidation in tumor cells." (PMID 37399661, 2023). "In support of this hypothesis, we found that antibody-mediated neutralization of IFNγ did not influence the absolute number of tumour-infiltrating monocytes and neutrophils, but significantly reduced the frequency of iNOS-expressing monocytes." (PMID 37316667, 2023). "Secondly, we quantified release of cytokines (i.e., IFNγ, IL-10, IL-2, IL-6, TNFα, GM-CSF, IL-12p70, IL-1b and IL-8) and granzyme B by using the MSD platform in supernatants collected from the TDCC assay with the tumor cell lines SK-CO-1, MKN-45 and H2122 after 48 h." (PMID 38087365, 2023). "Flow cytometric analysis of the tumor‐infiltrated immune cells revealed an increased CD4+ cells, CD4+Pd1+ cells, a reduced CD11b+F4/80+ macrophages, and a trend of increased CD8+ cells, CD8+Ifnγ+ cells, CD8+Pd1+ cells, CD4+Ifnγ+ cells, and B cells in FIN56‐treated tumors." (PMID 37026630, 2023). "We hypothesised that PARP14 might also act, therefore, as a negative feedback regulator in tumour cells, thereby antagonising IFNγ-stimulated tumour cell immunogenicity." (PMID 37752135, 2023). "According to the scRNAseq results, IFNγ and IL1β/TNFα are necessary to induce the highest levels of NOS2 and COX2 expression, which suggests that lymphoid cells could be a contributing factor in the tumor." (PMID 37169743, 2023). "This led us to hypothesize that IFNγ sensing by CD8 T cells might induce a negative feedback loop impacting their anti-tumor function." (PMID 36658158, 2023). "This is consistent with tumor volume being low only in Gpr68-/- male mice, suggesting the tumor-suppressing phenotype in male Gpr68-/- mice could be mostly due to higher IFNγ expression in NK cells, but not other cell types." (PMID 37350933, 2023). "In light of these data, it is hypothesized that V937 infection increases the production of interferon-gamma and CXCL10 by immune cells in the tumor microenvironment, particularly macrophages, which promote the response to anti-PD1 by properly guiding activated lymphocytes to dendritic cells." (PMID 37569757, 2023). "Local IFNγ and IFNγΔKRKR concentrations in the tumor were not different." (PMID 36732425, 2023). "In our settings, γδ T cells, with or without zoledronate treatment, did not respond with IFNγ secretion to xenograft-derived tumor cells, which might limit the protective immune response against tumor development." (PMID 37139603, 2023). "Consistent with these previous findings, the AFP TCR T cells with c-Jun overexpression from the tumor mass were less exhausted and less apoptotic and were better able to maintain their function of killing target tumor cells and producing more cytokines of IL2 and IFNγ." (PMID 37215108, 2023). "Consequently, these data suggest that IFNγ delivery at the tumor microenvironment alone, or in absence of CD4-TAM direct interaction, would not suffice for TAM reeducation and, most importantly, tumor clearance." (PMID 35903540, 2022). "In addition, the depletion of CD8+ T cells or treatment of IFNγ-KO mice led to the decreased activation of monocytes and TAMs, and no tumor regression." (PMID 35884605, 2022). "We further observed that the Vγ2 x PD-L1-induced Vγ2Vδ2 T cells’ cytotoxicity (killing EC50) towards tumor cells was correlated significantly with these tumor cells’ PD-L1 expression scores, while the release IFNγ EC50 showed a negative trend with the PD-L1 expression scores." (PMID 35784353, 2022). "An excessively increased inflammation state generated by tumor cells in a vicious circle participates in the release of pro-inflammatory factors by cells of the host immune system that are classified as procachectic factors: TNF-α, interleukins IL-1, IL-6, IL-8, and interferon gamma (IFNγ)." (PMID 35956359, 2022).
tumor (continued). "Correspondingly, G-CSF exposure had no bearing on tumor-cell-induced interferon γ (IFNγ) secretion." (PMID 35859694, 2022). "In tumor microenvironment upon interactions with tumor cells and stromal cells, NK cells lose CD16 expression and increase expression of CD56 surface receptor, leading to decreased cytotoxicity and increased production of cytokines, including interferon gamma (IFN-γ)." (PMID 35538218, 2022). "However, adding ICI to AAT and CXCR4 inhibition alleviated these resistance mechanisms further by increasing the amount of IFNγ and CD8+ T cells in the tumor center, indicating that vessels could be further normalized." (PMID 35712656, 2022). "As tumor-infiltrating lymphocytes (TILs) are the predominant source of IFNγ, they might upregulate negative feedback signals, hereby potentially contributing to tumor immune escape." (PMID 36419183, 2022). "To determine how the activation of CLL cells within the tumor microenvironment affects the cytotoxic effect of venetoclax, we treated cells derived from nine patients with CLL with 1 nM venetoclax alone and in combination with 100 ng/mL IFNγ, 10 nM PMA/ 1 μM ionomycin, and 100 ng/mL sCD40L for 24 h." (PMID 36209148, 2022). "Addition of IFNγ did not further enhance the expansion of potentially tumor-specific clones." (PMID 35377314, 2022). "The absence of interferon-gamma response mediated by the antigen processing machinery in tumor cells may result in their failure to be recognized by the immune system." (PMID 35903095, 2022). "Based on the observation of variance in the IFNγ-signalling of basal/squamous MIBC tumours, we hypothesised that this was related to the strength of the immune response provoked by the diverse neoantigen loads of these tumours." (PMID 36358715, 2022). "In tumor tissues with a high SIGLEC1/CD68 ratio, there was an increase in the infiltration and function of cytotoxic lymphocytes, based on the expression of the T cell receptor CD3 complex subunit (CD3E), natural cytotoxicity receptor (NCR1), and interferon gamma (IFNG)." (PMID 36266311, 2022). "After administration of a BRAFi in a BRAF-mutant melanoma model, CD40 ligand and interferon-gamma expression was increased on intratumoral CD4+ tumor-infiltrating lymphocytes (TIL), and regulatory T-cells and myeloid cells were decreased, suggesting anti-tumor modulation of the TME." (PMID 36505793, 2022). "Double-labeling of tumor cross sections with antibodies against human CD8 and human IFNγ followed by counting of CD8+ and IFNγ+ T cells clearly show marked infiltration of human CD8+ cells capable of releasing IFNγ into the tumor of PDX mice after treatment with p40 mAb, but not control IgG." (PMID 35053375, 2022). "Finally, human peripheral blood mononuclear cells treated with quercetin preferentially induced interferon gamma (IFN-γ) expression and synthesis while inhibiting IL-4 production resulting in a differential activation of Th1 cells, suggesting potential anti-tumor activity." (PMID 36339544, 2022). "In addition, not all tumor cells respond to IFNγ due to the presence of molecular aberrations in the IFNγ signaling pathways." (PMID 35681548, 2022). "Hence, the immunogenic action of IFNγ may be inevitably accompanied by an elevated immune evasion mechanism (PD-L1, IDO1, and Arg1) in the tumor microenvironment, and a specific therapeutic combination may overcome this unwanted effect." (PMID 34385592, 2022). "However, in vivo, the origin of IFNγ in the tumor tissue should not make any difference in the induction of general immunostimulatory processes." (PMID 36077380, 2022). "We also observed that TβRII+ EVs could led to a reduced cytotoxicity of tumor-infiltrating T cells (IFNγ+ or GZMB+ of CD8+ cells) and an increased exhaustion of tumor-infiltrating T cells (IFNγ+ or PD1+ of CD8+ cells) and a reduced fraction of FOXP3+ T regulatory cells in doxycycline-treated mice." (PMID 35915084, 2022).
tumor (continued). "In addition, IFNγ secreted by CD8+ T cells, which are activated by immunotherapy binds to IFNR, activates the JAK-STAT1-IRF1 signaling axis, and induces the expression of ACSL4 in tumor cells." (PMID 35847985, 2022). "Furthermore, in situ detection of the corresponding genes, TNFRSF9, IFNG and TNF, may also be considered as a strategy to rapidly and efficiently identify the functional characteristics of most tumor-specific TILs based on scRNA sequencing data." (PMID 36451828, 2022). "In another, which also included the GVAX anti-tumor vaccine, the anti-CSF-1R antibody given with anti-PD-1 therapy increased the number of intratumoral PD-1+ CD8+ and PD-1+ CD4+ T cells and increased their expression of IFNγ, a cytokine known to stimulate NK cells and neutrophils." (PMID 36077755, 2022). "This polarization was also confirmed via increasing in the expression level of cytokines such as interferon gamma (IFN-γ) and tumor necrosis factor alpha (TNF-α) which led to a significant reduction in the amount of interleukin 10 (IL-10), an immunosuppressive cytokine that promotes tumor growth." (PMID 35954362, 2022). "However, de novo MHC-II expression can be induced in non-haematopoietic cells including tumour cells by the inflammatory cytokine interferon gamma (IFNG)." (PMID 36259237, 2022). "In turn, acidification leads to the restriction of the production of interferon gamma (IFN-γ) by T cells that invade the tumor and prevents the activation of NK cells, which ultimately contributes to avoiding the immune response by the tumor and inhibits its growth." (PMID 36230479, 2022). "Immune phenotypic analysis of tumor-infiltrating T cells revealed that co-administration of CXB to the combination of CTX and ICB boosted the activation of CD8+ and CD4+ T cells, which displayed significantly higher production of IFNγ and surface expression of the activation marker CD44." (PMID 35440553, 2022). "Furthermore, among the mice treated with the combination therapy, levels of Th1 cytokine IFNγ and T-cell-recruiting chemokine CCL5 in the tumor were significantly lower in the B cell KO mice than in the WT mice, whereas the level of VEGF was significantly higher in the B cell KO mice." (PMID 35720386, 2022). "To determine if peritumoral LECs in vivo depended on IFNγ, we treated WT mice implanted with B16F10 with intraperitoneal injections of anti-IFNγ neutralizing antibody or IgG isotype control and analyzed MHC-II and PD-L1 expression in peritumoral LECs at 14 days post tumor implantation." (PMID 36362253, 2022). "After stimulation of lymphocytes with autologous tumor cells, we identified tumor-reactive T cells in lymphocytes isolated from non-metastatic lymph nodes of C126 by IFNγ ELISPOT assay, but we found tumor-reactive T cells in lymphocytes isolated from metastatic lymph nodes in two remaining cases." (PMID 35606862, 2022). "The secretion of IL-2 and IFNγ were measured and found to be very low when the tribodies were used in the absence of tumor cells, thus suggesting that the tribodies do not activate naïve T cells not expressing high levels of ICs and do not elicit off target cytokine release." (PMID 36071464, 2022). "Anti-tumour immunity was observed against B16 tumours expressing either constitutive or IFNγ inducible HLA-DP*0401 suggesting that the CD4 T cell response may exert both direct and indirect effects upon the tumour to promote inflammation and MHCII upregulation." (PMID 36544781, 2022). "Since p40 mAb upregulated human CD4+IFNγ+ and CD8+IFNγ+ T cells in the spleen of PDX mice, next we investigated whether p40 mAb treatment was capable of mounting these immune responses in vivo in tumor tissues." (PMID 35053375, 2022).